MTOR (mechanistic target of rapamycin kinase)
Diseases named in the same sentence as MTOR in open-access papers (continued):
Sharing a sentence is not in itself a finding about the gene and the disease.
osteosarcoma (continued). "At the mechanistic level, our findings indicate that HSPD1 may interact with ATP5A1 and increase ATP5A1 protein levels, thereby activating the AKT/mTOR pathway to mediate osteosarcoma progression." (PMID 39430254, 2024). "We found that the phosphorylation of mTOR was increased in osteosarcoma patients." (PMID 39015499, 2024). "Here, to determine whether they are pathway molecules for PRKCI to inhibit the proliferation of osteosarcoma cells, we detected the molecule expression of Akt-mTOR in SW1353 and U2OS cells when PRKCI was knocked down." (PMID 39015499, 2024). "Our current research elucidated the interaction between PRKCI and SQSTM1, demonstrating that PRKCI upregulated SQSTM1 and mediated critical functions in the proliferation and progression of osteosarcoma cells through the activation of the Akt/mTOR signaling pathway." (PMID 39015499, 2024). "We then asked whether ATP5A1 was involved in HSPD1-induced overactivation of the AKT/mTOR axis and the corresponding phenotypic changes in osteosarcoma." (PMID 39430254, 2024). "Previous research suggested that HOXD9 could influence the progression of osteosarcoma malignancy via the PI3K/AKT/mTOR pathway." (PMID 37974228, 2023). "VEGFA promotes the mTOR signaling in Osteosarcoma by promoting angiogenesis in the tumor." (PMID 37081847, 2023). "Furthermore, it has been found that inhibition of the PI3K/AKT/mTOR signaling pathway promotes apoptosis in osteosarcoma cells induced by chemotherapeutic agents, including DOX and methotrexate (MTX)." (PMID 37404761, 2023). "A study of osteosarcoma found that CREB promotes EMT by activating the PI3K/AKT/mTOR pathway." (PMID 36717805, 2023). "Most of the targeted therapies for osteosarcoma have focused on signaling pathways such as human epidermal growth factor receptor (HEGR2), insulin-like growth factor 1(IGF1), and mammalian target of rapamycin (mTOR), which appear overactive in osteosarcoma tumors." (PMID 37175397, 2023). "However, the results regarding their efficacy are conflicting, and the use of mTOR inhibitors in clinical practice for osteosarcomas remains limited." (PMID 37109122, 2023). "Our study revealed 19 genes involved in the mTOR signaling pathway of Osteosarcoma viz." (PMID 37081847, 2023). "Compelling research has revealed that PI3K/AKT/mTOR signalling could participate in promoting the osteosarcoma process by regulating a variety of target genes." (PMID 37539493, 2023). "Together, our results revealed that modulators of RARb, PPARg, LXRs and Rev-Erba inhibit osteosarcoma growth both in vitro and in vivo through the mTOR signaling pathway, suggesting that treatment with these NR modulators is a novel potential therapeutic strategy." (PMID 36681687, 2023). "In contrast, AIM2 might repress proliferation by inactivating the phosphatidylinositol-3-kinase/protein kinase B/mammalian target of rapamycin (PI3K/AKT/mTOR) signaling pathway in osteosarcoma cells." (PMID 36742336, 2023). "Our study revealed that the expression of RILP was associated with favorable prognosis of osteosarcoma and RILP inhibits proliferation, migration, and invasion and promotes autophagy in osteosarcoma cells via Grb10-mediated inhibition of the PI3K/AKT/mTOR signaling pathway." (PMID 37789274, 2023). "This included three drugs (Buparlisib, LJI308, and Pictilisib) targeting the PI3K/mTOR pathway, which has been identified as a potential drug target in osteosarcoma, and consistent with this, patients with high TMEindex in this study did have higher activation of this pathway." (PMID 37055822, 2023). "LncRNA UCA1 promoted osteosarcoma metastasis by activating mTOR signaling pathways." (PMID 36807122, 2023). "Moreover, we further proposed that the anti-osteosarcoma effect of baicalin is mediated by accumulating ROS to inhibit the PI3K/Akt/mTOR, ERK1/2 and β-catenin pathways." (PMID 35573641, 2022).
osteosarcoma (continued). "However, in osteosarcoma, the IGF-1R/mTOR pathway has been implicated as a driver of anti-apoptotic signals and aberrant growth in many cancers making the pathway an attractive target for potential therapies." (PMID 35284040, 2022). "To explore whether the effect of HULC on osteosarcoma cells depends on PI3K/Akt/mTOR signaling pathway, we added LY294002, an inhibitor of PI3K signaling pathway." (PMID 36213832, 2022). "Moreover, doxycycline triggers Notch1 activation, apoptosis, and autophagy by suppressing the PI3K/AKT/mTOR axis in osteosarcoma cells." (PMID 36139919, 2022). "In addition, STEAP2 expression induced epithelial–mesenchymal transition (EMT) via the PI3K/AKT/mTOR axis and facilitated osteosarcoma cell infiltration and migration." (PMID 36316642, 2022). "Knockdown of KRT17 may also decrease the viability and Warburg effect of osteosarcoma cells by significantly affecting the AKT/mTOR/hypoxia-inducible factor 1α (HIF1α) pathway and interrupting the expression of relevant genes." (PMID 36009022, 2022). "A recent study reported that magnesium released from biomaterials could activate the AMPK/mTOR signaling pathway, thus upregulating autophagy in osteosarcoma cells." (PMID 36412862, 2022). "Moreover, upregulation of STEAP2 promotes EMT via activation of the PI3K/AKT/mTOR axis thereby enhancing the metastatic and invasive capabilities of osteosarcoma cells." (PMID 36316642, 2022). "Though single-agent therapies against IGF-1R or mTOR have proved ineffective in osteosarcoma, the ability to co-target these pathways using novel biologically-targeted agents would be expected to yield synergistic anti-cancer activity, as has been observed in preclinical bone sarcoma models." (PMID 35284040, 2022). "In addition, recent evidence also showed that Xist is overexpressed in osteosarcoma and promotes cancer cell proliferation and migration via mechanisms such as regulation of microRNAs (miRNAs) and mTOR and other signaling pathways." (PMID 36187119, 2022). "The link between the mTOR pathway and miR-1224 has also been reported in osteosarcoma cells." (PMID 36430972, 2022). "Furthermore, osteosarcoma cell lines respond to therapeutic inhibition of the PI3K/mTOR pathway both in vitro and in vivo." (PMID 36052285, 2022). "One exploration illustrated that Src could mediate PI3K/Akt/mTOR pathway to regulate autophagy of osteosarcoma cells." (PMID 34316408, 2021). "Our results indicate that the control of magnesium availability could be a useful strategy for inhibiting osteosarcoma cell growth, and support the hypothesis that mTOR may represent a target for the antiproliferative effect of magnesium deficiency." (PMID 33923895, 2021). "Furthermore, it has been reported that the inhibition of the Akt/mTOR pathway and NF-κB can enhance the effects of anti-cancer drugs and radiation and suppresses tumor angiogenesis in osteosarcoma cells." (PMID 34026649, 2021). "Furthermore, silencing of GPNMB has been shown to reduce the proliferation of osteosarcoma cells through suppressing mTOR signaling." (PMID 34445242, 2021). "To confirm whether the effect of cordycepin on the inhibition of osteosarcoma growth is mediated by suppression of the AKT/mTOR signaling pathway, we treated osteosarcoma cells with cordycepin for 48 h and performed western blotting." (PMID 34953496, 2021). "Importantly, inhibition of Akt/mTOR signaling following caffeine treatment was reported in various cell types such as in osteosarcoma cells, hematopoietic myeloid cells, and SH-SY5Y cells." (PMID 34371919, 2021). "Network pharmacology and bioinformatics research inferred that aloin may inhibit osteosarcoma through the PI3K/AKT/mTOR pathway." (PMID 34819120, 2021). "In addition, circ_0001785 has been reported to decrease the apoptosis of osteosarcoma cells through activation of the PI3K/Akt/mTOR pathway." (PMID 34660257, 2021).
osteosarcoma (continued). "In addition, it had reported that autophagy and apoptosis were triggered in osteosarcoma MG-63 cells with honokiol treatment, which was associated with increasing the expression of LC3II while decreasing PI3K, phosphorylation-Akt, and p-mTOR expression levels." (PMID 32054506, 2020). "Compared to normal bone tissue, metabotropic glutamate receptor (mGluR) has been reported to be highly expressed in osteosarcoma tissues as well as related to poor prognosis, and it is well known that active mGluR signaling is linked to the PI3/AKT/mTOR pathway." (PMID 33210231, 2020). "TRIM14 induces the activation of the AKT/mTOR pathway in osteosarcoma cells." (PMID 33634104, 2020). "Since the PI3K/Akt/mTOR signaling pathway has been shown to be associated with metastasis of trophoblast cells, and DDX46 was reported to regulate the PI3K/Akt pathway in osteosarcoma." (PMID 33817228, 2020). "Our results suggest that EEF1D exerts its effect on osteosarcoma by promoting Akt-mTOR and Akt-Bad signaling pathways, which could be the mechanism by which EEF1D promotes tumor progression." (PMID 29510727, 2018). "We further examined whether EEF1D knockdown could affect the Akt-mTOR and Akt-Bad signaling pathways in osteosarcoma cells using Western blotting analysis, and the results revealed that EEF1D knockdown inhibited the phosphorylation of Akt, mTOR, and Bad." (PMID 29510727, 2018). "Taken together, out data support that EEF1D may play an important role in osteosarcoma cell growth by enhancing the Akt-mTOR and Akt-Bad signaling pathways." (PMID 29510727, 2018). "In the osteosarcoma genome project the tumors are driven by increased mTOR pathway activity, which can occur via multiple different mutations, including loss of PTEN, a negative regulator of mTOR." (PMID 28640831, 2017). "Prior studies of mTOR inhibitors in osteosarcoma have demonstrated a hint of activity for targeting this pathway but were not adequate to assess the activity of PI3K/mTOR inhibition in osteosarcoma due to study design, lack of molecular correlation, and/or the number of patients enrolled." (PMID 27441088, 2016). "These therapies include indirectly targeting MYC in combination with the PI3K pathway, mechanistic target of rapamycin (mTOR), or histone deacetylases (HDACs) for the treatment of T-cell acute lymphoblastic leukemia, pancreatic ductal adenocarcinoma, and osteosarcoma, respectively." (PMID 27081479, 2016). "However, when viewed as a whole, the available clinical data suggest potential activity of inhibition of the PI3K/mTOR pathway in osteosarcoma, which warrants further investigation." (PMID 27441088, 2016). "However, a recent complementary genomic and pathway analysis identified PI3K/mTOR pathway aberrations in a subset of osteosarcoma samples." (PMID 27441088, 2016). "Our screen confirms mTOR signaling as a potential target to treat osteosarcoma." (PMID 26807203, 2015). "Nevertheless, the precise role mTOR plays in the regulation of the malignant stemness of osteosarcoma cells remains unclear." (PMID 25853231, 2015). "The PI3K/Akt/mTOR pathway has been reported to contribute to osteosarcoma progression." (PMID 26510912, 2015). "All these results suggested that extrinsic 4-HNE may inactivate AKT/mTOR signaling and promote the cell apoptosis in human osteosarcoma cell line MG63." (PMID 24711740, 2014). "Based on these results, we conclude that attenuating the PI3K/Akt/mTOR pathway may be effective in a subset of osteosarcomas." (PMID 24447333, 2014). "Therefore, the role of PIK3/AKT/mTOR pathway regulators needs to be explored in osteosarcoma patients." (PMID 25126591, 2014). "The mTOR inhibitor ridaforolimus has been studied in a phase II trial of patients with advanced bone sarcomas and this study revealed improved progression-free survival in advanced sarcomas including osteosarcoma." (PMID 24599309, 2014). "Indeed, inhibition of the mTOR pathway has been shown to be effective in a model of murine osteosarcoma." (PMID 24216993, 2013).
osteosarcoma (continued). "The results from these studies may provide the useful insight concerning the potential therapeutic value of mTOR inhibitors in osteosarcoma treatment." (PMID 24216993, 2013). "In addition, it was recently discovered that mTOR signaling is activated in human osteosarcoma and correlates with surgical stage, metastasis, and disease-free survival." (PMID 23476113, 2013). "A role for mTOR signaling in osteosarcoma metastasis is slowly evolving." (PMID 23476113, 2013). "Little is known about the status of mTOR biology in canine osteosarcoma." (PMID 20543980, 2010). "Accordingly, before the dog could be integrated within the development path of mTOR inhibitors in osteosarcoma patients, preliminary studies with rapamycin in dogs were necessary." (PMID 20543980, 2010). "Using the infrastructure of the Comparative Oncology Trials Consortium many of these complex questions were asked within a relevant population of dogs with osteosarcoma to inform the development of mTOR inhibitors for future use in pediatric osteosarcoma patients." (PMID 20543980, 2010). "It has been suggested that inhibition of the mammalian target of the rapamycin (mTOR) pathway may be effective in osteosarcoma." (PMID 18782081, 2008). "Overexpression of PRKCI enhanced the level of SQSTM1, p-mTOR, and p-AKT and inhibited the level of LC3B-II, indicating that overexpression of PRKCI could enhance the level of SQSTM1 and inhibit the level of autophagy through the Akt-mTOR pathway in osteosarcoma cells." (PMID 39015499, 2024). "Moreover, BKA blocked the effect of ATP5A1 overexpression on mTOR signaling in osteosarcoma cells." (PMID 39430254, 2024). "Thus, we hypothesized that the AKT/mTOR pathway could serve as a potential mechanism through which HSPD1 facilitates the advancement of osteosarcoma." (PMID 39430254, 2024). "Moreover, the phosphorylation level of mTOR in osteosarcoma patients increased." (PMID 39015499, 2024). "Therefore, combined targeting of RILP and the PI3K/AKT/mTOR signaling pathway may provide a new therapeutic strategy for osteosarcoma." (PMID 37789274, 2023). "Furthermore, numerous data have demonstrated that PI3K/AKT/mTOR (mTOR: mammalian target of rapamycin kinase) inhibitors may have strong suppressive activity against osteosarcoma progression." (PMID 37958539, 2023). "Therefore, we hypothesized that the PI3K/AKT/mTOR pathway might be one of the main downstream pathways that promote the development and occurrence of osteosarcoma." (PMID 38053170, 2023). "Our transcriptomic and immunoblotting data indicated that mTOR- and MAPK-associated pathways, including the ERK1/2, AKT, AMPK and mTOR pathways, respond to the NR modulators in the early stage of treatment and are associated with the inhibition of osteosarcoma growth." (PMID 36681687, 2023). "In addition, Some different signaling networks in osteosarcoma, including RANKL/RANK, Wnt, Notch, PI3K/Akt/mTOR, and mechanotransduction pathways, contribute to osteosarcoma progression and metastasis and tumor heterogeneity, which certainly looks worthy of further investigation." (PMID 36759884, 2023). "In our work, we discovered that in vivo and in vitro overexpression of PSMD14 was adversely correlated with a poor prognosis in osteosarcoma; PSMD14 may induce malignant osteosarcoma characteristics by the PI3K/AKT/mTOR pathway, according to a preliminary study." (PMID 38053170, 2023). "Similarly, AOS-SO4 inhibited osteosarcoma cell growth through the MEK1/ERK/mTOR pathway in vivo." (PMID 35418575, 2022). "In addition, similar to EFEMP2, STEAP2 may induce EMT through the PI3K/AKT/mTOR axis and facilitate osteosarcoma cell infiltration and migration." (PMID 36316642, 2022). "Moreover, WB also confirmed that CLTC knockdown could inhibit the activation of AKT/mTOR signaling in osteosarcoma." (PMID 34185412, 2021).
osteosarcoma (continued). "In addition, our study showed that low Sestrin2 expression can effectively reduce autophagy of human osteosarcoma cells after chemotherapy, increase p-mTOR expression, decrease Bcl-2 expression, promote osteosarcoma cell apoptosis, and slow down tumour progression in NU/NU mice." (PMID 34646824, 2021). "However, in stark contrast, miR-210 increases cell proliferation in human osteosarcoma cell lines by modulating the Akt-mTOR signaling pathway by directly silencing PIK3R5 (phosphoinositide-3-kinase regulatory subunit 5) expression through directly targeting the PIK3R5 3′UTR." (PMID 35052722, 2021). "In addition, arsenic sulfide, the main active ingredient of the traditional Chinese medicine realgar, has been reported to induce G2/M cell cycle arrest, apoptosis, and autophagy via the activation of ROS/JNK signaling and the blockade of the AKT/mTOR pathway in human osteosarcoma cells." (PMID 34093198, 2021). "In this study, it appears that IOP may regulate the proliferation, migration, invasion, and apoptosis of osteosarcoma cells by inhibiting the activation of the Akt/mTOR and NF-κB signaling pathway and further supplement the understanding of the antitumor mechanism of IOP." (PMID 33282634, 2020). "Thus, we hypothesize that PI3K/Akt/mTOR pathway might be a potential mechanism for the effects of Rg3 on osteosarcoma aggressiveness." (PMID 29750154, 2018). "ZA may actually have greater efficacy against surgically incurable macroscopic osteosarcoma used as a single agent or in combination with the mTOR inhibitor everolimus or the VEGFR tyrosine kinase inhibitor pazopanib, targeting tumor cell proliferation and angiogenesis, respectively." (PMID 27127605, 2016). "Similarly to RAD001, imatinib mesylate inhibit mTOR pathway in human and murine osteosarcoma cells." (PMID 24599309, 2014). "Ginsenoside CK was also reported to inhibit the growth, migration and invasion, and survival of human osteosarcoma cells by triggering apoptosis and interfering with the PI3K/mTOR/p70S6K1 signaling pathway." (PMID 40507179, 2025). "Another study demonstrated that ginsenoside Rg3 suppressed the proliferation of osteosarcoma cells and induced apoptosis through various signaling pathways, including the PI3K/Akt/mTOR pathway." (PMID 40507179, 2025). "In conclusion, in vivo assays revealed that TRIM17 positively regulates the activation of the AKT/mTOR signaling pathway via FTO-mediated PDK1 expression, thereby enhancing osteosarcoma growth." (PMID 41145484, 2025). "Recent advancements in genetic and molecular research have elucidated critical pathways involved in osteosarcoma pathogenesis, such as the PI3K/Akt/mTOR axis, VEGF-mediated angiogenesis, and PD-1/PD-L1 signaling." (PMID 41346999, 2025). "Previous studies have demonstrated that miR-664b-3p directly targets Rheb, a key regulator of the Rheb/mTOR/c-MYC signalling pathway, which promotes glycolysis and tumour growth in osteosarcoma (OS) cells." (PMID 41004517, 2025). "Numerous studies have shown that during the occurrence and development of osteosarcoma, the PI3K/Akt/mTOR signaling pathway is often in an activated state." (PMID 41180454, 2025). "Phellamurin, a flavonoid glycoside found in plants, decreases the viability of osteosarcoma cells and promotes apoptosis by inhibiting the PI3K/AKT/mTOR pathway." (PMID 40959060, 2025). "In human osteosarcoma cells, NCTD showed dose-dependent inhibition of proliferation and induction of apoptosis through the c-Met/Akt/mTOR signaling pathway." (PMID 39940982, 2025). "In osteosarcoma, the abnormal activation of the AKT/mTOR pathway has been confirmed to be directly related to the invasive ability and lung metastasis potential of tumor cells." (PMID 41145484, 2025). "Alisertib, an aurora kinase inhibitor, promotes apoptosis and autophagy in human osteosarcoma U-2 OS and MG-63 cells by activating mitochondrial pathways and inhibiting the p38 MAPK/PI3K/Akt/mTOR signaling pathway." (PMID 38914997, 2024).